SLC15A1 (solute carrier family 15 member 1)
Description:
Electrogenic proton-coupled amino-acid transporter that transports oligopeptides of 2 to 4 amino acids with a preference for dipeptides. Transports neutral and monovalently charged peptides with a proton to peptide stoichiometry of 1:1 or 2:1 (By similarity). Primarily responsible for the absorption of dietary di- and tripeptides from the small intestinal lumen (By similarity). Mediates transepithelial transport of muramyl and N-formylated bacterial dipeptides contributing to recognition of pathogenic bacteria by the mucosal immune system.
Synonyms: PEPT1; HPECT1; HPEPT1
Tractability: Small molecule: a high-quality ligand is known; it belongs to a druggable protein family. Antibody: UniProt places it where antibodies can reach, with high confidence; its Gene Ontology location is reachable by antibodies, with high confidence; UniProt predicts a signal peptide or a membrane-spanning region. PROTAC: its protein half-life has been measured; a small molecule that binds it is known.
Target class: SLC superfamily of solute carriers; SLC15 family of peptide transporters; Electrochemical transporter; Transporter
Gene: Protein-coding gene on chromosome 13 (98,683,801 to 98,752,836, reverse strand). Ensembl gene ENSG00000088386.
Subcellular location: Apical cell membrane
Subcellular location (Human Protein Atlas): Cytosol; Nucleoplasm
Pathways (Reactome):
Transport of small molecules: Proton/oligopeptide cotransporters
Gene Ontology:
Molecular function: dipeptide transmembrane transporter activity; peptide:proton symporter activity; tripeptide transmembrane transporter activity; oligopeptide transmembrane transporter activity; proton-dependent oligopeptide secondary active transmembrane transporter activity; transmembrane transporter activity
Biological process: dipeptide import across plasma membrane; oligopeptide transmembrane transport; tripeptide import across plasma membrane; oligopeptide transport; proton transmembrane transport; transmembrane transport
Cellular component: apical plasma membrane; plasma membrane; membrane; brush border
Genetic constraint (gnomAD): Loss-of-function variants: 62 observed, 68.55 expected, observed/expected ratio (o/e) 0.9, 90% interval 0.74 to 1.12. The upper end of that interval is the gene's LOEUF score, 1.12, which puts it in group 4 of 6, group 1 being the genes least tolerant of losing a copy. Missense variants: 724 observed, 780.89 expected, observed/expected ratio (o/e) 0.93, 90% interval 0.87 to 0.99. Synonymous variants: 270 observed, 288.34 expected, observed/expected ratio (o/e) 0.94, 90% interval 0.85 to 1.04.
Homologues: Orthologues: chimpanzee SLC15A1 (99% identical), macaque SLC15A1 (93% identical), mouse Slc15a1 (85% identical), rat Slc15a1 (84% identical), pig SLC15A1 (83% identical), dog SLC15A1 (83% identical), guinea pig SLC15A1 (81% identical), rabbit SLC15A1 (80% identical), tropical clawed frog slc15a1 (63% identical), zebrafish slc15a1b (58% identical), zebrafish slc15a1a (56% identical). Paralogues in human: SLC15A2 (47% identical), SLC15A4 (17% identical), SLC15A3 (16% identical), SLC15A5 (14% identical).
Diseases named in the same sentence as SLC15A1 in open-access papers:
SLC15A1 is named in the same sentence as 59 diseases in open-access papers, as found by Europe PMC text mining. Sharing a sentence is not in itself a finding about the gene and the disease. The quoted sentences say what the papers report.
pancreatic cancer (8 papers, 2014 to 2024). "A couple of recently published studies reported on the expression/activity of the H+/peptide cotransporter SLC15A1/PEPT1 in pancreatic cancer." (PMID 36765717, 2023).
hepatocellular carcinoma (4 papers, 2017 to 2024). A malignant tumor that arises from hepatocytes. "The non-synonymous genetic variant rs2257212 (SLC15A1 c.1048C>T, p.L350F) was associated with prolonged progression-free survival (PFS) in patients with unresectable hepatocellular carcinoma (HCC) treated with sorafenib." (PMID 32806706, 2020).
colorectal cancer (3 papers, 2021 to 2023). A primary or metastatic malignant neoplasm that affects the colon or rectum. "Indeed, re-expression of epigenetically silenced SLC15A1/PEPT1 sensitized colorectal cancer cells for drug treatment as recently demonstrated." (PMID 37208732, 2023).
prostate carcinoma (3 papers, 2017 to 2022). A carcinoma that arises from epithelial cells of the prostate gland. "Similar peptide conjugated prodrug strategies are being pursued to target cancer compounds to proton-coupled peptide transporter PEPT1/SLC15A1, which is overexpressed by some prostate cancers." (PMID 28350329, 2017).
Bladder Cancer (2 papers, 2023 to 2024). "Rs4646227 of SLC15A1 has been identified as an independent indicator in bladder cancer, and SLC15A1 has been found to be a potential predictor of recurrence in LUAD." (PMID 39593730, 2024).
lung carcinoma (2 papers, 2020 to 2021). "A total of 1962 lung cancer cases were divided into high and low expression groups by the median signal of SLC15A1 with the 207254_at probe." (PMID 34168674, 2021). "Regarding lung cancer, only one study showed increased SLC15A1 expression compared with that in normal tissue." (PMID 34168674, 2021). "The results suggested that PEPD, SLC15A1, and SLC5A3 were candidates for individual lethal genes specific to lung cancer, and pairs of CBS-SLC7A11, CBS-SLC3A2, CMPK1-PTDSS1, CMPK1-PLD2 were candidate synergistic lethal genes specific in the tumors." (PMID 32085724, 2020).
asthma (1 paper, 2016). "The two strongest associations involved two SNPs newly implicated in asthma, rs17655581 and rs7980829, located near SLC15A1 and in an intergenic region, respectively." (PMID 27445529, 2016). "The closest gene, SLC15A1, is not known to be involved in asthma but is known to cause inflammation in the intestine by the mediation of intracellular uptake of bacterial products." (PMID 27445529, 2016).
atherosclerosis (1 paper, 2021). A disease characterized by the build-up of fatty material and calcium deposition in the arterial wall resulting in partial or complete occlusion of the arterial lumen. "Finally, it may be stated that the protective effects of CTP against atherosclerosis might be attributed to its action on ECs, because the expression level of SLC15A1, which is the major transporter of CTP, is low in SMCs, and SMCs are barely responsive to CTP." (PMID 34209567, 2021).
colon adenocarcinoma (1 paper, 2023). "Given its role in the cellular uptake of decitabine and its regulation by PBA, we also investigated the prognostic value of SLC15A1/PEPT1 expression among 440 colon adenocarcinoma patients." (PMID 37208732, 2023).
kidney cancer (1 paper, 2021). Primary or metastatic malignant neoplasm involving the kidney. "For other major cancer types, SLC15A1 was significantly increased in kidney cancer in 5 cases, with 3 opposite results." (PMID 34168674, 2021).
lung adenocarcinoma (1 paper, 2021). A carcinoma that arises from the lung and is characterized by the presence of malignant glandular epithelial cells. "We found that there was little difference between lung adenocarcinoma and squamous cell carcinoma in SLC15A1, SLC15A2 and SLC15A3." (PMID 34168674, 2021).
tumor (26 papers, 2008 to 2025). "The upregulation of SLC15A1 in cancer cells coupled to the naturally occurring acidic pH in the tumor microenvironment provide the optimal conditions for the cancer cells to take up these small peptides to support their amino acid nutrition." (PMID 36765717, 2023). "First, we considered transcript expression of DNMT1 and the cellular uptake transporter of decitabine, i.e., SLC15A1/PEPT1 in clinical samples of 275 tumor and 41 histologically proven normal resection material." (PMID 37208732, 2023). "Strikingly, PBA treatment recovered the expression of the decitabine drug-uptake transporter SLC15A1, thus enabling high tumor drug-loads." (PMID 37208732, 2023). "Strikingly, PBA specifically induced expression of the decitabine uptake transporter SLC15A1, and this improved intracellular loading of tumor cells for sustained tumor cell eradication." (PMID 37208732, 2023). "Only SLC15A1 had a different expression between the normal lung tissue and tumor samples, its transcription expression was very low (TPM < 1)." (PMID 34168674, 2021).
cancer (23 papers, 2009 to 2024). A tumor composed of atypical neoplastic, often pleomorphic cells that invade other tissues. "Slc15a1 is involved in drug absorption in the small intestine and has been linked to several cancers and metastasis." (PMID 22260314, 2012). "In the present study, we have found yet another mechanism for niclosamide to interfere with amino acid nutrition in cancer cells that involves the function of the H+/peptide cotransporter SLC15A1/PEPT1." (PMID 36765717, 2023). "SLC15A family members from SLC15A1 to SLC15A4 were searched in 20 major cancers through the Oncomine database." (PMID 34168674, 2021). "SLC15A2 had a controversial expression pattern with SLC15A3 across the pan-cancer study, where SLC15A1 showed a down-regulated expression in most of solid cancers and SLC15A4 displayed an up-regulated pattern." (PMID 34168674, 2021). "According to our selection standard for those cancers with unique analysis, the studies included were SLC15A1 (7:24), SLC15A2 (13:48), SLC15A3 (27:13), and SLC15A4 (12:3)." (PMID 34168674, 2021). "PEPT1 (SLC15A1) has been widely studied in cancers and anticancer drug transportation." (PMID 34168674, 2021). "However, in most cancer types, SLC15A1 showed relatively lower expression." (PMID 34168674, 2021). "SLC15A3 and SLC15A4 were different from SLC15A1 and SLC15A2, with increased patterns in pan-cancer compared with normal tissue." (PMID 34168674, 2021). "Unlike SLC15A1 and SLC15A2, which are frequently studied in the cancer field, the roles of SLC15A3 and SLC15A4 in cancer are quite opaque." (PMID 34168674, 2021).
infection (9 papers, 2007 to 2025). The state of being infected such as from the introduction of a foreign agent such as serum, vaccine, antigenic substance or organism. "At individual gene expression level several transporter genes (Cacna1i, Slc4a1, Slc15a1) and immune response genes (Igsf4d, Ilf1, Csf2) showed no overlap possibly due to infection kinetics." (PMID 17850650, 2007).
neurodegenerative disease (1 paper, 2023). A disorder of the central nervous system characterized by gradual and progressive loss of neural tissue and neurologic function. "We also observed SLC15A1, a peptide transporter protein associated with digestion and absorption, on chromosome 13 and a positive selection signal for the NIPA1 gene, which causes neurodegenerative diseases in chromosome 15." (PMID 36721228, 2023).
SLC15A1 also shares sentences with these, for which no sentence is quoted: colitis (15 papers); inflammatory bowel disease (11); Obesity (5); gastric cancer (4); colon carcinoma (3); Diabetes (3); short bowel syndrome (3); inflammation (2); liver cancer (2); Sepsis (2); type 2 diabetes (2); Allergy (1); Anorexia (1); Anxiety (1); bacterial infections (1); bipolar disorder (1); bladder tumors (1); blood cancer (1); cardiovascular diseases (1); cholangiocarcinoma (1); chronic myelogenous leukemia (1); chronic renal failure (1); clear-cell carcinoma (1); coccidiosis (1); colorectal adenocarcinoma (1); Crohn disease (1); cyst (1); glioma (1); Hartnup disorder (1); hyperthyroidism (1).
A further 14 diseases each share a sentence with SLC15A1 in 1 paper.